L1CAM (L1 cell adhesion molecule)
Diseases named in the same sentence as L1CAM in open-access papers (continued):
Sharing a sentence is not in itself a finding about the gene and the disease.
melanoma (continued). "Regarding neoplastic ones, gynecological tumors, some neuroendocrine and neural tumors, as well as melanomas, showed L1CAM expression, whereas most carcinomas of other sites did not express L1CAM." (PMID 40870967, 2025). "Interestingly, L1CAM, which is a FUT8 target and mediator of cancer progression in melanoma, showed downregulation in this case, suggesting an alternate mechanism in RCCs." (PMID 38703764, 2024). "To this end, we measured the levels of L1CAM in melanoma and neuroblastoma cells with or without the expression of α-syn." (PMID 37286800, 2023). "Cohesion between melanoma cells is mediated by N-cadherin, αvβ3-integrin, L1-CAM, AL-CAM and MCAM/MUC18 that are not expressed on melanocytes." (PMID 33870460, 2021). "L1CAM and CD82 expression levels in melanocytes and melanoma cells follow a similar profile." (PMID 34439879, 2021). "Besides promoting proliferation, ERK-dependent gene expression downstream of L1CAM is reported for ESCC and melanoma, resulting in gene expression involved in migration and invasion." (PMID 31455004, 2019). "L1-CAM protein levels were similarly reduced in both FER iKD and FER KO melanoma cells, indicating that the extent of FER downregulation in response to silencing by shRNA treatment is sufficient to induce biological alterations that are very similar to those observed upon FER gene inactivation." (PMID 30909648, 2019). "To compare our findings in ECs with a non-endothelial cell type, we used the mouse melanoma cell line B16, which also expresses high levels of endogenous L1CAM, but does not express L1-ΔTM." (PMID 30829570, 2019). "For this purpose, we used a spontaneous metastasis xenograft mouse model of human BRAF wildtype melanoma cells with and without RNAi mediated L1CAM knockdown." (PMID 29432466, 2018). "Remarkably, active but not total AR positively correlates with fuco-L1CAM predominantly in stage IIB-III melanomas—pathological staging that is expected to functionally require altered cell adhesion and invasive dynamics to promote subsequent distal metastasis." (PMID 38326303, 2024). "Indeed, L1CAM has been defined as a negative prognostic factor in melanoma, breast cancer, gastric cancer, colon cancer, pancreatic cancer, non-small cell lung cancer, kidney cancer, etc., as elegantly reviewed elsewhere." (PMID 32429448, 2020). "However, until now it has never been demonstrated that L1CAM has a direct functional role in melanoma metastasis, e.g. by an animal model." (PMID 29432466, 2018). "For L1CAM low melanoma, a partial compensation for the lack of L1CAM could be an overexpression of JAG1 (Jagged 1), modulating Notch signaling." (PMID 29432466, 2018).
breast carcinoma (49 papers, 2008 to 2025). "Circulating tumor cells (CTCs) and L1 cell adhesion molecule (L1CAM) are associated with breast cancer (BC) metastasis." (PMID 41306535, 2025). "In breast cancer, L1 cell adhesion molecule (L1CAM) expressed in cancer-associated fibroblasts stimulates ERK signaling via integrin α5β1 in cancer cells and promotes tumor growth." (PMID 35618735, 2022). "L1CAM, an adhesion molecule that is associated with poor prognosis in certain breast cancers, was expressed at much lower levels in the KO cells." (PMID 32374759, 2020). "Thus, L1CAM is validated further to be a potential early diagnostic marker in breast cancer progression and a target for breast cancer therapy." (PMID 20840789, 2010). "In this study, CTCs were classified into EMT subtypes using the CanPatrol system, and the expression of the molecular marker L1CAM was assessed to systematically evaluate their relationship with lymph node metastasis in breast cancer." (PMID 41306535, 2025). "This study also provides the first systematic assessment of L1CAM expression in peripheral blood CTCs in breast cancer, with a positivity rate of 71.6%, predominantly localized to H-CTCs." (PMID 41306535, 2025). "These platforms identified tumor-specific membrane targets, such as GD2 and L1CAM, for NB and breast cancer (BC) using patient-derived organoids (PDO) and xenograft models." (PMID 40129921, 2025). "In breast cancer, L1CAM expression is observed in all molecular subtypes but shows a preference for TNBC and is associated with aggressive behavior." (PMID 38183514, 2024). "A correlation analysis was performed using publicly available mRNA profiles from two cohorts of breast cancer patients to investigate the relationship between L1CAM and FOXC1." (PMID 38183514, 2024). "Because CAF-mediated ERK phosphorylation specifically occurs in the peripheral regions of breast cancers, which are surrounded by stroma, L1CAM is possibly involved in the local progression of breast cancers." (PMID 36831085, 2023). "The overexpression of the cell adhesion molecule (L1CAM) has been correlated with tumour aggressiveness and poor prognosis in patients and promotion of breast cancer motility in vitro." (PMID 36347335, 2023). "The expression of L1CAM is increased in luminal B breast cancer, and its expression is related to disease recurrence and higher levels of Ki-67 expression." (PMID 36338974, 2022). "Hypoxia-induced HIF-1 is considered a stimulant of the extravasation of breast cancer to lung cancer via the HIF-1-mediated L1 cell adhesion molecule (L1CAM) and angiopoietin-like 4 (ANGPTL4)." (PMID 36551540, 2022). "While L1CAM increases the adherence of breast cancer cells to EC monolayers via hemophilic or heterophilic interactions, ANGPTL4 blocks EC−EC interactions, facilitating the vascular metastasis of breast cancer cells to the lung parenchyma." (PMID 36551540, 2022). "In breast carcinoma, cleavage of the L1-cell adhesion molecule (L1-CAM) promotes cell migration on fibronectin and laminin." (PMID 36439249, 2022). "It has been shown that the ALCAM present on activated endothelial cells interacts with L1CAM in breast cancer cells, mediating tumour-endothelial interactions." (PMID 34680335, 2021). "Other metastases genes associated with poor prognosis in breast cancer, such as CEACAM6, COL17A1, CXCL8, TNFAIP3, SEMA7A and L1CAM, are also attenuated with SP receptor antagonist treatment." (PMID 34359773, 2021). "It has been reported that brain metastatic cells from breast cancer and lung cancer induce large amounts of serine protease inhibitors (SERPINs) to prevent plasminogen activator (PA) destruction of L1CAM and mediate the spread of metastatic cells." (PMID 34202399, 2021). "In human breast cancer specimens, the number of fibroblasts expressing L1CAM, Mint3 and MT1-MMP was higher in cancer regions than in adjacent benign regions." (PMID 28504692, 2017).
breast carcinoma (continued). "Such a role of tumor-derived L1CAM in the crosstalk with vascular endothelium has been further investigated in breast cancer cells, where L1CAM mediates the interaction with the vasculature during metastatic dissemination to the brain and to the lung." (PMID 28134764, 2017). "For MDA-MB231 breast cancer cells we showed, that the over-expression of L1CAM or its up-regulation by the EMT-inducer TGF-β augmented matrigel invasion and migration on ECM components." (PMID 25510351, 2014). "Using the human cancer genome atlas database and two independent breast cancer cohorts we find that L1CAM is inversely correlated with androgen receptor (AR) expression." (PMID 25510351, 2014). "Our results warrant the use of L1CAM staining for the improved diagnosis of primary breast cancer and suggest a link between L1CAM expression and the general bad prognosis of TNBCs." (PMID 25510351, 2014). "We analyzed mRNA and protein expression data from different breast cancer cohorts for L1CAM, estrogen receptor, progesterone receptor, Her-2 and Androgen receptor (AR) and correlated the data." (PMID 25510351, 2014). "Overexpression of AR in MDA-MB436 breast cancer cells decreased L1CAM expression at the protein and mRNA level and CHIP-analysis revealed binding of AR to the L1CAM promoter region." (PMID 25510351, 2014). "In conclusion, the present paper strongly supports the use of L1CAM in breast cancer diagnosis and suggests a link between L1CAM expression and the general bad prognosis of TNBCs." (PMID 25510351, 2014). "Li and Galileo found that soluble L1CAM (sL1), produced by proteolytic cleavage of membrane-bound L1CAM, acted as a chemoattractant for breast cancer cells in transmigration assays and this effect was neutralized using sL1 blocking antibodies." (PMID 22272201, 2012). "ANGPTL4 inhibits EC (endothelial cell)-EC interactions, whereas L1CAM promotes the adherence of breast cancer cells to ECs." (PMID 23241400, 2012). "Our analysis corroborated their study on L1CAM localization in intracellular vesicles and cleavage at the membrane-proximal end in different breast cancer cell lines." (PMID 20840789, 2010). "In view of previous studies, our current work aims at elucidating the function of L1CAM, especially its soluble form, in breast cancer cell migratory processes." (PMID 20840789, 2010). "Our current study focused on the potential role of soluble L1CAM in breast cancer cell adhesion to extracellular matrix proteins, migration, and invasion." (PMID 20840789, 2010). "From previously established databases of breast cancer clinical samples or in vitro cultured cell lines, the L1CAM gene or the region in the X chromosome where it is located (Xq28) has been found to be abnormally amplified in some cases." (PMID 20840789, 2010). "In our work here, analysis of L1CAM expression in three breast cancer cell lines, MDA-MB-435, MDA-MB-231 and MDA-MB-468, revealed that MDA-MB-468 cells showed relatively low L1CAM expression both at mRNA and protein levels compared to the other two." (PMID 20840789, 2010). "For example, L1CAM, GATA4, CCNB1, CDKN1C, and FEN1 have been reported for their association with breast cancer: L1CAM was shown to inhibit the growth of breast carcinoma cells." (PMID 18237428, 2008). "We previously used this assay to study L1CAM-dependent breast cancer cell migration." (PMID 39518060, 2024). "A soluble form of L1CAM has been found in HER2-enriched primary breast cancer patients." (PMID 36338974, 2022). "Furthermore, L1CAM (L1 cell adhesion molecule) on breast cancer cells has been shown to interact with ALCAM on endothelial cells promoting tumour-endothelial interactions." (PMID 34680335, 2021). "With the exception of breast cancer, L1CAM-ECD stimulated migration and invasion in all studies." (PMID 31455004, 2019). "Both L1CAM-SV and L1CAM-FL can promote motility in breast cancer cells." (PMID 31455004, 2019).
breast carcinoma (continued). "Conversely, breast cancer cells were shown to use α5β1 integrin to engage with upregulated L1CAM in tumor-associated fibroblasts, but do not rely on this integrin to interact with endothelia." (PMID 31455004, 2019). "For instance, L1CAM expression increases with progression of breast cancer." (PMID 29615539, 2018). "In accord with previous study showing that manipulation of the level of L1CAM affects the migration properties of breast cancer cells, we observed that downregulation of L1CAM attenuates migration of proliferating BJ cells, supporting the role of L1CAM in cell locomotion." (PMID 29615539, 2018). "The data also strongly advocate the use of L1CAM assessment in breast cancer diagnosis." (PMID 25510351, 2014). "Kaplan-Meier curves showed a decreased survival of L1CAM positive breast cancer patients." (PMID 25510351, 2014). "Here we have analyzed more closely the distribution of L1CAM expression in breast cancer." (PMID 25510351, 2014). "We next tried to confirm the inverse correlation of L1CAM and AR in in breast cancer cell lines." (PMID 25510351, 2014). "Furthermore, hypoxia has been show to induce L1CAM-mediated breast cancer cell adhesion to tumor microvasculature." (PMID 24884715, 2014). "Here we analysed the expression of L1CAM breast cancer subtypes." (PMID 25510351, 2014). "However, further investigation is required to determine whether FOXC1 directly or indirectly regulates L1CAM in breast cancer cells." (PMID 38183514, 2024). "FOXC1 and L1CAM may share common mechanisms in breast cancer progression." (PMID 38183514, 2024). "Thus, inflammatory conditions might increase Mint3 expression in fibroblasts of tumour tissues and higher MT1-MMP/Mint3 expression might induce L1CAM expression in fibroblasts of human breast cancer tissues." (PMID 28504692, 2017). "Thus, in breast cancer AR is a negative regulator of L1CAM expression." (PMID 25510351, 2014). "Consequently, abnormal L1CAM expression may be a good marker for detection of breast cancer progression and metastatic potential." (PMID 20840789, 2010). "Interaction of L1CAM and the erbB3 receptor was reported to enhance the response of erbB3 to the EGF-like factors, neuregulins, in MCF-7 breast cancer cells." (PMID 38263290, 2024). "In our study, we analyzed publicly available RNA sequencing data from breast cancer patients, and identified a positive correlation between FOXC1 and L1CAM expression (Pearson correlation coefficient = 0.370, 0.244)." (PMID 38183514, 2024). "In breast cancer cells, instead, L1CAM itself and the other Ig-CAM ALCAM were reported to establish homophilic and heterophilic interactions, respectively, with L1CAM in ECs, promoting the adhesion of tumor cells to the endothelium." (PMID 28134764, 2017). "This revealed a number of significant hotspots of epigenetic deregulation, centred around important breast cancer genes, including FOXA2, PAX6 and L1CAM, with the two largest modules mapping to the WNT and FGF signalling pathways, respectively." (PMID 26823093, 2016). "In the breast carcinoma cell line MCF7, upregulation of L1CAM has been shown to lead to disruption of E-cadherin-containing adherens junctions and thereby to increased transcriptional activity of β-catenin." (PMID 25860483, 2015). "For breast cancer, angiopoietin-like 4 (ANGPTL4) and L1 cell adhesion molecule (L1CAM) are the two important molecules that mediate vascular metastasis of hypoxic breast cancer cells to the lungs." (PMID 23241400, 2012). "Moreover, TGF-β was shown to upregulate L1CAM to trigger binding of integrins, resulting in induction of IL-1β secretion and EMT promotion in pancreatic and breast cancers." (PMID 38263290, 2024). "In breast cancer cells, the inhibition of HIF (HIF-1α and HIF-2α) resulted in the inhibition of breast cancer tumor growth and lung metastasis by suppressing the expression of angiopoietin-like 4 (ANGPTL4) and L1 cell adhesion molecule (L1CAM)." (PMID 36984785, 2023).
breast carcinoma (continued). "Furthermore, L1CAM, CDKN1C, and FEN1, which have been reported to be relevant to breast cancer – the most sensitive subtype to docetaxel among the nine NCI-60 cancer subtypes – were clustered just next to the drug vector." (PMID 18237428, 2008). "Mechanistic studies are also warranted to elucidate L1CAM’s functional role in CTC biology and evaluate its therapeutic potential, alongside integration of immune microenvironmental features to construct more comprehensive models for breast cancer metastasis monitoring and intervention." (PMID 41306535, 2025). "This was in contrast with the expression of known HIF target genes involved in breast cancer metastasis not included in the hypoxia signatures (LOX, LOXL2, LOXL4, CCL2, L1CAM, ANGPT1, and ANGPT2), whose expression showed a positive correlation with the signatures." (PMID 29540773, 2018).
Hydrocephalus (45 papers, 2009 to 2025). Hydrocephalus is an active distension of the ventricular system of the brain resulting from inadequate passage of CSF from its point of production within the cerebral ventricles to its point of absorption into the systemic circulation. "This multimodal approach strengthens confidence that the c.1380-1G>A mutation directly drives pathogenic splicing disruptions relevant to L1CAM-associated hydrocephalus." (PMID 40520226, 2025). "X‐linked hereditary hydrocephalus (XLH) is a congenital form of hydrocephalus caused by variants in the L1CAM gene on the X chromosome." (PMID 40822607, 2025). "The last discovered synonymous variant in L1CAM was identified in a pregnant woman who reported five consecutive pregnancies with fetal hydrocephalus in 20195." (PMID 38263409, 2024). "In conclusion, we report the recurrence of a hemizygous L1CAM variant, which is responsible for hydrocephalus in male fetuses." (PMID 38263409, 2024). "Ultimately, we screened 35 unrelated fetuses prenatally suspected of corpus callosum agenesis accompanied with hydrocephalus for L1CAM gene variants by Sanger sequencing." (PMID 34914080, 2022). "Pathogenic mutations of L1CAM can cause L1 syndrome, referred to as a variety of disease spectrums characterized by hydrocephalus." (PMID 35571029, 2022). "L1CAM gene mutation detection can be offered to fetuses presented corpus callosum agenesis accompanied with hydrocephalus." (PMID 34914080, 2022). "In the present study, we reported two novel variants of L1CAM in two unrelated Chinese families with fetal hydrocephalus history." (PMID 35571029, 2022). "Thirty-five isolated cases prenatally suspected of corpus callosum agenesis accompanied with hydrocephalus were screened to acquire detection rate of L1CAM gene variant." (PMID 34914080, 2022). "We screened 35 unrelated fetuses prenatally suspected of corpus callosum agenesis accompanied with hydrocephalus for L1CAM gene variants to acquire a detection rate of L1CAM gene variant in these cases." (PMID 34914080, 2022). "Defects in L1CAM are associated with L1 syndrome, which encompasses a wide phenotypic spectrum from severe hydrocephalus and prenatal death (HSAS) to a milder phenotype (MASA), even occur within the same family." (PMID 35177665, 2022). "In non-cilia related hydrocephalus, mutations in L1CAM (encoding L1 cell adhesion molecules, gene located at Xq28) are common in CH, generally referred to as L1 syndrome (L1CAM-associated hydrocephalus) or X-linked hydrocephalus." (PMID 34233705, 2021). "The L1-CAM mutations in humans cause the expansion of brain ventricles, hydrocephalus, mental retardation, and deficiency of corpus callosum." (PMID 32902807, 2021). "In Liebau's study (Liebau, Gal, Superti‐Furga, Omran, & Pohl, 2007), a mutation at the beginning of intron 18 of L1CAM was related to the agenesis of corpus callosum, adducted thumbs, hydrocephalus, and mental retardation." (PMID 31756056, 2020). "The purpose of the study was to report a new disease‐causing mutation site of L1CAM, making a small step forward in the pathogenesis of hydrocephalus." (PMID 31756056, 2020). "The objective of the study was to report a new disease‐causing mutation site of L1CAM, and gain further insight into the pathophysiology of hydrocephalus." (PMID 31756056, 2020). "AP1S2 is also located in the X chromosome and, like L1CAM, underlies several syndromic defects, one of which is hydrocephalus." (PMID 30518636, 2019). "L1CAM pathogenic variants are responsible for a wide spectrum of phenotypes, now termed L1, the most severe form being Hydrocephalus with Stenosis of the Aqueduct of Sylvius (HSAS; MIM#307000)." (PMID 28460636, 2017). "In the 2 cases presented here, adducted thumbs in the setting of severe hydrocephaly were detected prenatally with 3D ultrasound and the L1CAM mutation was confirmed by molecular genetic analysis." (PMID 26078893, 2015).